SMIM10 (small integral membrane protein 10)
Synonyms: CXorf69
Tractability: Antibody: UniProt predicts a signal peptide or a membrane-spanning region.
Gene: Protein-coding gene on chromosome X (134,990,991 to 134,992,473, forward strand). Ensembl gene ENSG00000184785.
Subcellular location: Membrane
Gene Ontology:
Cellular component: membrane
Homologues: Orthologues: chimpanzee SMIM10 (100% identical), pig SMIM10 (72% identical), zebrafish smim10l3 (41% identical). Paralogues in human: SMIM10L2A (66% identical), SMIM10L2B (66% identical), SMIM10L3 (59% identical), SMIM10L1 (52% identical).